KRT19 (keratin 19)
Diseases named in the same sentence as KRT19 in open-access papers (continued):
Sharing a sentence is not in itself a finding about the gene and the disease.
tumor (continued). "HSP60, glutathione-S-transferase pi (GST-Pi), α-enolase, TCP1β and cytokeratin 19 (CK19) were detected in the large majority of the samples, and significant overexpression in tumor tissue as compared with matching normal mucosa was confirmed for the first four proteins, but not for CK19." (PMID 21973086, 2011). "Notably, the elevated CYFRA21–1 levels observed in poorly differentiated LUAD may stem from increased cytokeratin-19 fragment release during rapid tumor proliferation, a phenomenon previously reported in undifferentiated malignancies." (PMID 41505423, 2026). "KRT19, an intermediate filament protein, contributes to cytoskeletal organization and epithelial integrity in luminal subtypes (e.g., MCF7 and T47D) and is associated with cell adhesion and tumor progression via interactions with KRT8, KRT18, and EPCAM, as suggested by STRING analysis." (PMID 40806403, 2025). "Besides, LAMC2, KRT8 and KRT19 spatially patterned tumor markers shared ‘epidermis development’ and ‘cellular component morphogenesis’ spatially patterned pathways in the tumor region, which may indicate the proliferation of cancer cells." (PMID 36243975, 2023). "Notably, NEJ634 expressed the highest levels of Krt19 among the 4 tumor samples." (PMID 37414763, 2023). "As indicated by cytokeratin-19 (K19) immunofluorescence and hematoxylin & eosin staining of single cell-derived branching organoids and corresponding orthotopic tumors, the system indeed displays prominent features of tumor morphogenesis in vivo, including the formation of tubular structures." (PMID 36064947, 2022). "Cytokeratin 19 serum fragment 21-1 (Cyfra21-1), squamous cell carcinoma-associated antigen (SCCAg), tissue polypeptide-specific antigen (TPS), carcinoembryonic antigen (CEA), Fe protein, and circulating tumor cells (CTCs) are tumor markers for the diagnosis and prognosis of HNSCC." (PMID 35845594, 2022). "Importantly, KRT19 can be used as a molecular marker for reverse transcriptase PCR (RT-PCR) and ELISA-mediated detection of disseminated tumor cells in regional lymph nodes (LNs), peripheral blood (PB) and bone marrow from susceptible cancerous patients 12, 35-36." (PMID 33442422, 2021). "Segregation of these patients into KRT19-high and low expression groups did not reveal significant relationship with clinicopathological parameters of sex, age, tumor size, location, but noticeably associated with tumor grading, TNM staging." (PMID 33442422, 2021). "Indeed, the DRP markers such as Prom1, EpCAM, Krt19, and Sox9 detected in AH, were also induced in non-tumor liver tissue (NTL) of mice subjected to DEN injection and tumor promotion with WAD as compared to normal liver or tumor tissues, suggesting a more selective increase of DRPs in NTL." (PMID 33173221, 2020). "Neither CYFRA21-1 in serum nor its encoding KRT19 gene in the tumour changed significantly." (PMID 22905093, 2012). "Spatial analyses revealed distinct immune cell communities in primary and metastatic PDAC, in which cytokeratin 19 (CK19+) cells clustered differentially with αSMA+, CD3+, and CD68+ cells, depending on the tumor site." (PMID 41418102, 2026). "To investigate TIC-derived GAS6 suppression of tumor immunity via AXL/MERTK on Reg-TAMs, we used Krt19-DreER Axin2-creER R26-Ai66 mice for AKT/YAP/SB hydrodynamic injection and sorted Reg-TAMs and epithelial cell adhesion molecule+/Tom+ (EpCAM+Tom+) TICs." (PMID 39774471, 2025). "We evaluated the effects of KRT19 inhibition and anti-PD-1 on NSCLC growth and immune infiltration using xenograft tumor models, flow cytometry and CIBERSORT." (PMID 41345704, 2025).
tumor (continued). "Employing a novel algorithm capable of super‐resolution analysis of tumour ecosystems,15we first identified tumour cells based on the expression of EPCAM, TG, KRT18 and KRT19." (PMID 39810624, 2025). "Abnormal tumor markers, such as CEA, NSE, cytokeratin 19, and SCC, were chosen for further research." (PMID 40361899, 2025). "The canonical markers EPCAM and KRT19 identified tumor cells, while CD3D, CD2, PTPRC, CD14, AIF1, CD79A, and COL1A2 validated non-tumor cells." (PMID 39955556, 2025). "The corresponding heatmap depicted the high-expression profiles of various cell types in marker genes such as KRT19, VWF, ACTA2, CD68, and TPSB2, effectively distinguishing immune, stromal, and tumor cell components." (PMID 41488617, 2025). "The levels of tumor markers, including AFP, carcinoembryonic antigen (CEA), carbohydrate antigen (CA) 12-5/19-9/72-4, and cytokeratin 19 (CK19), were all within the normal range." (PMID 40538841, 2025). "Conversely, TGT significantly reduced tumor markers: CA125, CEA, and cytokeratin-19 fragment (CYFRA21-1)." (PMID 40575781, 2025). "For cancer mortality, it identified proteins involved in tumour proliferation and microenvironment modulation (CEACAM5, KRT19 and SDC1), demonstrating COMET’s capacity to uncover meaningful molecular mechanisms." (PMID 40008295, 2025). "In our tumor epithelial dataset, genes with the strongest positive correlation with TM4SF1 expression within the HV tumor cells were EMP1, CLDN4, EZR, and KRT19." (PMID 40527915, 2025). "This confirmed that stromal transcripts (Fap and Acta2) were mapped to the mouse genome, while tumor cell-intrinsic transcripts (MUC1 and KRT19) were human reads." (PMID 40508010, 2025). "Laboratory tests revealed elevated tumor markers, including carcinoembryonic antigen (CEA) (5.5 ng/mL) and cytokeratin 19 fragment (CYFRA 21‐1) (5.1 ng/mL)." (PMID 41350121, 2025). "For instance, serum tumor markers such as carcinoembryonic antigen (CEA), cytokeratin 19 fragment (CYFRA 21-1), and neuron-specific enolase (NSE) reflect disease severity and treatment outcomes through concentration fluctuations." (PMID 41154834, 2025). "In addition, we performed Kaplan-Meier survival analysis in Kaplan-Meier Plotter and illustrated that tumor KRT19 expression was positively correlated to poor prognosis in NSCLC patients, suggesting that KRT19 might serve as an indicator for overall survival of NSCLC patients." (PMID 41345704, 2025). "We propose serum cytokeratin 19 fragment (CYFRA 21-1) and tumor contact length (TCL) as complementary prognostic factors." (PMID 41374349, 2025). "To further validate the clinical utility of the model, we constructed a decision curve analysis (DCA) to compare the prognostic performance of the MRPL family model with that of other established tumor biomarkers, including AFP, MKI67, and KRT19." (PMID 41399509, 2025). "Combination of Krt19 knockdown in LLC and anti-PD-1 immunotherapy remarkably attenuated tumor growth compared with all other groups." (PMID 41345704, 2025). "To substantiate this classification, we examined the expression of hallmark canonical cell markers of cancer epithelial cells (EPCAM, SOX4, KRT7, KRT18, KRT19, KRT8) in C1 (normal epithelial cells) and the other clusters (tumour epithelial cells)." (PMID 38445456, 2024). "Tumor marker neuron-specific enolase (NSE) showed a declining trend over treatment and carcinoembryonic antigen (CEA) and cytokeratin 19 (CK19) remained within the normal range." (PMID 39015492, 2024). "On the other hand, from methylation analysis, we observed that the promoter region of HGs such as KRT19, MMP1, COL11A1, SDC1, FN1, and COL5A1 is significantly methylated in normal tissue than in tumor tissue." (PMID 38639039, 2024).
tumor (continued). "The epithelial cell marker genes EPCAM, KRT19, and KRT7 were used to annotate tumor cells that were further verified copy number variations." (PMID 39474422, 2024). "In this study, we intend to comprehensively define the diagnostic value of individual and combined detection of serum IL-6 related to the traditional tumor markers carcinoembryonic antigen (CEA) and cytokeratin 19 fragment (CYFRA21-1) for AIS." (PMID 38529301, 2024). "The high expression of tumor-related genes (EPCAM, CD24, CDH1, ELF3, KRT18, KRT19, KRT8, and MUC1) in groups 10 and 11 suggests that cells in these groups are tumor cells." (PMID 38693422, 2024). "In this study, we noticed that the promoter regions of five HGs, such as KRT19, MMP1, COL11A1, SDC1, FN1, and COL5A1 were highly methylated in normal compared to tumor patients." (PMID 38639039, 2024). "The cutoff values for the tumor markers were defined as 5.0 ng/mL or higher for carcinoembryonic antigen (CEA) and 3.5 ng/mL or higher for soluble fragment of cytokeratin 19 (CYFRA21‐1) in accordance with the institutional standards." (PMID 38400801, 2024). "Multivariate modelling, including all proteins independent of their association in the univariate analysis, identified a model for separating benign conditions from malign tumours (stage I–IV) consisting of three proteins; WFDC2, KRT19 and RBFOX3." (PMID 39068297, 2024). "WFDC2 can be measured as a tumor marker in Japan, and thus, GDF15 was excluded and WFDC2, CHI3L1, and KRT19 were used as the variables of classification." (PMID 36331721, 2023). "EMT genes like KRT19, CTNNB1 and TWIST1 and the hypoxia marker HIF1A were significantly changed in tumors, indicating altered tumor microenvironment." (PMID 37170215, 2023). "Consistently, the cytokeratin tumor markers, KRT8, KRT18, and KRT19, were most abundantly expressed in these epithelial cells." (PMID 37430270, 2023). "The diagnostic efficiency of the two lncRNAs was compared with that of the currently used classic tumor markers, carcinoembryonic antigen (CEA) and cytokeratin 19 fragment (CYFRA21‐1)." (PMID 35871358, 2023). "After quality control, 11,390 tumor cells (TG, EPCAM, KRT18, and KRT19) and 6,808 normal cells (TG, TPO) were obtained for subsequent analysis." (PMID 35359404, 2022). "Small duct intrahepatic CCA is a peripherally located tumour that expresses immunohistochemical markers of cholangiolar differentiation, such as CK7, cytokeratin 19 (CK19) and epithelial membrane antigen." (PMID 36008616, 2022). "Tumor cells (cluster 0, 2, 5, 6, 7, 8, 10, and 11) were distinguished by the expression of CD24, KRT19, and EPCAM." (PMID 36291687, 2022). "Organoid cells were identified by the expression of the tumor markers KRT18 and KRT19 whereas CAFs were characterized by DCN and LUM expression." (PMID 36273171, 2022). "LCSL cells express liver stem cell markers, including epithelial cell adhesion molecule (EpCAM), cytokeratin 19 (CK19), OV6 and Sal-like protein 4 (SALL4), and account for approximately 10% of the overall tumor tissues." (PMID 35223840, 2022). "The correlation between serum exosomal miR-27b expression and tumor markers carcinoembryonic antigen 125 (CA125), carcinoembryonic antigen (CEA), and cytokeratin 19-soluble fragment (CYFRA21-1) was analyzed using the Pearson analysis." (PMID 35582197, 2022). "The levels of the tumor markers CEA (carcinoembryonic antigen), NSE (neuron-specific enolase), CYFRA21-1 (cytokeratin 19 fragment), and SCC (squamous cell carcinoma antigen) were higher in the aLC group than those in the eLC group (P<0.05)." (PMID 36330467, 2022).
tumor (continued). "We retrospectively quantified apoptotic responses and tumor-stroma cell proportions in PDOs via 3D immunofluorescence imaging through annexin A5, α-smooth muscle actin (α-SMA), and cytokeratin 19 (CK-19) levels." (PMID 36282600, 2022). "In this case, the clear tumor cells showed positivity of MUC-1, cytokeratin 7, and cytokeratin 19, and showed negativity of vimentin and neuroendocrine markers, which indicate pancreatic clear cell carcinoma with ductal phenotype." (PMID 36140448, 2022). "Over the years, other tumor markers for HCC have been proposed, such as Golgi protein 73 (GP73), Glypican-3 (GPC3), and cytokeratin 19 (CK-19)." (PMID 36119529, 2022). "It represented a stronger prediction factor than tumor grade, stage or classical PDAC markers such as CEA, MUC16, MUC1, CA199, KRT19 and NSE, and also performed better than any m5C-score gene taken individually." (PMID 36060802, 2022). "We confirmed this result within Krt19+ PDACs; very few EGFP+ PDAC epithelial cells were observed within Krt19+ tumor areas before tamoxifen injection." (PMID 33393460, 2021). "Hence, the serum level of KRT19 fragments could be applied in the clinic as a tumor marker." (PMID 33442422, 2021). "Currently, traditional tumor markers, such as carcinoembryonic antigen (CEA) and cytokeratin 19 fragment (CYFRA 21-1), are used to diagnose and evaluate ESCC progression but their sensitivity and validity are insufficient for early ESCC detection." (PMID 34518524, 2021). "The localised KLK6 expression in tumour cells (identified by KRT19) and macrophages (represented by CD68) in the invasive areas underscores the potential for KLK6-targeted inhibitors that interfere with tumour-biological events in a context-dependent manner." (PMID 34439122, 2021). "Over the years, additional tumor markers for HCC have been suggested, such as Golgi protein 73 (GP73), Glypican-3 (GPC3), cytokeratin 19 (CK-19), among others." (PMID 33849479, 2021). "Three of the identified key genes (FKBP10, KRT19, and SPANXB1) negatively correlated with the infiltration of CD8+ T cells, which is the lymphocytes primarily responsible for immune-mediated tumor cell death." (PMID 35096583, 2021). "To identify the most potent tumor cell-targeted cytotoxic drugs, we compared the GR-corrected IC50 estimates of the drugs between the KRT19+ and VIM+ cells." (PMID 34604070, 2021). "HCC in patients with expression of tumor stem cell markers such as EpCAM, PROM1 and KRT19 tend to be aggressive and chemoresistant." (PMID 33173221, 2020). "To determine if tumor organoids recapitulate the biology and architecture of the PDX models, we analyzed organoid sections by H&E stain and using a molecular marker (cytokeratin 19) that is expressed in ductal epithelia of the pancreas." (PMID 32990680, 2020). "Plasma levels of reported candidate circulating tumor biomarkers SCC-Ag, cytokeratin 19 fragment (CYFRA21-1), soluble Fas (sFas), and soluble FasL (sFasL) were also analyzed and compared with those of circulating pGSN." (PMID 32545773, 2020). "The KRT19 was already described as a possible biomarker for PDAC, and patients with upregulation of KRT19 presents poor differentiation, large tumor size, lymph node metastasis, and invasion." (PMID 32005189, 2020). "Usefulness of molecular techniques for detecting tumor markers, such as carcinoembryonic antigen (CEA), cytokeratin 19 (CK-19), and cytokeratin 20 (CK-20), have been reported." (PMID 32992913, 2020). "Tumor cells in organoids and PDX tumors expressed cytokeratin 19, demonstrating that cells in culture and PDX models retained pancreatic epithelial differentiation." (PMID 32990680, 2020).
tumor (continued). "A comparison between the miRNAs and traditional tumor markers [CEA, NSE, and cytokeratin 19 fragment 21-1 (Cyfra21-1)] and radiological diagnosis was performed." (PMID 32596148, 2020). "To determine the fate of PROM1+ cells in tumor development, we stained the liver sections with visible tumors with anti-GFP and anti-KRT19 antibodies." (PMID 33173221, 2020). "The typical mPDAC markers, e.g. EPCAM, cytokeratin 19, CD133 etc., were indeed enriched in these cells, validating the tumor cell identity." (PMID 30799483, 2019). "Cytokeratin 19 (CK19) positivity in HCC cells was well correlated with the clinical and pathological features of tumor aggressiveness and poor prognosis." (PMID 30774659, 2019). "Currently, traditional tumor markers, such as CEA and cytokeratin 19 fragment (Cyfra) 21–1, are used to diagnose and evaluate ESCC progression." (PMID 31722716, 2019). "Krt19 is expressed in a subset of HCC with poor prognosis and it was correlated with increased tumor size, decreased differentiation, epithelial-mesenchymal transition, metastasis, and microvascular invasion." (PMID 30177788, 2018). "We investigated four tumour markers in Croatian patients: carcinoembryonic antigen (CEA), neuron-specific enolase (NSE), cancer antigen 125 (CA-125), and cytokeratin 19 fragment (CYFRA 21-1)." (PMID 29472801, 2018). "Some of these genes, such as KRT19, EMP1, and PARP2, have evidence from previous studies, which indicate their higher expression levels in the original tumors compared with PDX tumor cells." (PMID 29534550, 2018). "In contrast, only three luminal markers showed immuno-staining in the tumor transplants (KRT7, KRT19, and CD24)." (PMID 30550540, 2018). "Lastly, KRT19 and GPRC5A can act as tumor suppressors in other cancers, but have pro-oncogenic functions in PDAC." (PMID 29675033, 2018). "Immunohistochemically, tumor cells were strongly positive for thyroglobulin (Tg), thyroid transcription factor-1 (TTF-1), galetin-3, cytokeratin-19 (CK19), and human bone marrow endothelial cell-1 (HBME-1)." (PMID 26791568, 2016). "Additional transcripts such as KRT-19,MAGE-A3, and PBGD have also been used for the detection and molecular characterization of circulating tumor cells." (PMID 25398926, 2015). "Periostin, keratin-1, nm-23 protein, etc., were up-regulated in tumour stroma; HSP 70, keratin-19, Rho GDP dissociation inhibitor (GDI) β, superoxide dismutase, etc., were down-regulated in tumour stroma." (PMID 26184160, 2015). "The tumor cells were positive for chromogranin A, synaptophysin, CD99, cytokeratin 19, pan-cytokeratin and β-catenin, and also showed diffuse immunoreactivity for AFP and human chorionic gonadotrophin." (PMID 25886790, 2015). "HPCs/biliary markers including cytokeratin 7 (K7), cytokeratin 19 (K19), Epithelial cell adhesion molecule(EpCAM) and OV6 were stained in the HCC tumor tissues." (PMID 26311117, 2015). "Several tumor markers, such as carcinoembryonic antigen (CEA), squamous cell carcinoma antigen (SCC) and cytokeratin 19-fragment (CYFRA 21-1), are used in clinical diagnosis as well as in patient’s follow-up." (PMID 24551190, 2014). "KRT19, CEACAM5 and EPCAM mRNA had been reported previously as promising tumor cell markers in LNs from NSCLC patients, whereas SFTPA and SFTPC were novel genes in this context." (PMID 23671585, 2013). "Immunohistochemically, the resected tumor stained positively for epithelial markers of epithelial membrane antigen (EMA) and cytokeratin 19 (CK 19), and mesenchymal markers of smooth muscle actin (SMA) and vimentin." (PMID 23426899, 2013).